IDH1 (isocitrate dehydrogenase (NADP(+)) 1)
Diseases named in the same sentence as IDH1 in open-access papers (continued):
Sharing a sentence is not in itself a finding about the gene and the disease.
astrocytomas (continued). "IDH1/2 mutation status is a prognostic marker used to differentiate between astrocytoma and GBM as IDH mutations are associated with more optimistic prognosis." (PMID 38615034, 2024). "This study focused on task design as prerequisite for reliable application of crowdsourced data in ML in the context of labeling astrocytes and tumor cells in high-grade IDH1-mutated astrocytoma." (PMID 38263411, 2024). "The sarcomatous portion of the recurrence is distinctly astrocytic and clonally derived from the initial IDH-mutant astrocytoma, as demonstrated by an identical 17p CnLOH break-point and IDH1-R132C point mutations." (PMID 39707480, 2024). "According to the 2021 WHO Classification, the highest number of patients with IDH1 mutation in plasma was found in the astrocytoma G II (40%), and G III (30%), oligodendroglioma (20%), astrocytoma G IV (10%)." (PMID 38172718, 2024). "BAY 1436032 demonstrated no toxicity in vitro or in vivo and significantly prolonged the survival of mice implanted with IDH1-R132H-mutated human astrocytoma." (PMID 38660136, 2024). "IDH-mutant astrocytoma grade 4 was defined as a diffusely infiltrative astrocytic glioma with an IDH1 or IDH2 mutation that exhibited microvascular proliferation or necrosis, CDKN2A/B homozygous deletion, or any combination of these features." (PMID 39457569, 2024). "In this work, we developed a task design for advanced cell annotations in MSIs of IDH1-mutated high-grade astrocytoma for paid crowds." (PMID 38263411, 2024). "For this, labels were prepared based on tumor-specific markers (e.g., ATRX-loss in high-grade IDH1 astrocytoma as represented in Var1)." (PMID 38263411, 2024). "In one case, the detection of an IDH1 D375N mutation led to re-classification from giant cell glioblastoma to astrocytoma CNS-WHO grade 4." (PMID 39143272, 2024). "For IDH1(R132H) + astrocytomas, vaccines targeting the IDH1(R132H) mutation advance precision medicine." (PMID 39215399, 2024). "Another benefit to methylation profiling is that it can inclusively recognize oncogenic variants of IDH1/2 and can be further subclassed into tumor types based on epigenetic marks (for example, astrocytoma or oligodendroglioma)." (PMID 39596840, 2024). "TERT mutations have been reported to be closely associated with IDH1/2 mutations and 1p/19q-codeletion in oligodendroglioma, but less well correlated in astrocytomas." (PMID 36831683, 2023). "Next, tumor DNA sequencing failed to capture the mutation in IDH1, however, CSF ctDNA sequencing showed a rare mutation of R132C in IDH1, and corrected the tumor diagnosis into IDH1-mutated astrocytoma, WHO IV, according to CSF test." (PMID 37822669, 2023). "In adult humans, the T2FMM sign is a highly accurate biomarker for IDH1‐mutated, 1p/19q non‐codeleted astrocytomas, with specificity and sensitivity as high as 100% and 31%, respectively." (PMID 37246729, 2023). "In contrast to supratentorial IDH-mutant astrocytomas, infratentorial astrocytomas frequently harbor non-IDH1 R132H mutations such as IDH1 R132C/G and IDH2 R172S/G limiting the sensitivity of IDH1 R132H immunohistochemistry." (PMID 36717507, 2023). "WHO grade 4 tumors with IDH1-mut should mostly belong to astrocytoma, IDH1-mut and WHO grade 4 (exclude CDKN2A/B mutation)." (PMID 37029174, 2023). "We also analyzed Gal-1 levels in tumors harboring IDH-1 mutations, a group of patients with a good prognosis who are currently classified as having an astrocytoma grade 4." (PMID 36980184, 2023).
astrocytomas (continued). "Those HGG harbouring the IDH1 mutation (astrocytoma grade 4) have likely progressed from LGG, previously called secondary glioblastoma." (PMID 36050369, 2022). "The majority (90%) of astrocytomas and oligodendrogliomas carry a canonical IDH1 R132H mutation, which can be detected by IDH1 (R132H), while other mutations should be detected through the sequencing involving IDH1 and IDH2 genes." (PMID 35991838, 2022). "For example, astrocytomas harboring an IDH1 mutation progress towards a highly aggressive phenotype." (PMID 36353533, 2022). "A first-in-humans, multicenter, single-arm open-label phase I trial (NOA-16, NCT02454634), which included 33 patients with newly diagnosed WHO grade 3 and 4 IDH1(R132H) mutated astrocytoma, demonstrated safety and immunogenicity of IDH1-vac." (PMID 35158978, 2022). "Although mutations in H3F3A are found exclusively in a subtype of grade IV pediatric astrocytoma, mutations in IDH1/2 genes are very rare in children under 14 years of age." (PMID 36293551, 2022). "Oligodendroglioma (ODG) and astrocytoma are both classified by mutations in IDH1 or IDH2 (IDH) with the former also harboring 1p19q codeletion and the later retaining 1p19q." (PMID 35526077, 2022). "Here we describe a case of a patient with an IDH-mutant astrocytoma, in which both IDH1 and IDH2 mutations were detected within the same tumour." (PMID 36286062, 2022). "In 2008, hotspot mutation in IDH1 gene was identified in grade II/III astrocytomas and oligodendrogliomas, and in secondary GBM that developed from these lower-grade lesions." (PMID 34764443, 2022). "It is reported that in more than 70% of WHO grade 2/3 cases and secondary astrocytoma, grade 4, carry a heterozygous missense mutation at the IDH1 codon 132, the substitution of Arg132 with histidine (IDH1-R132H)." (PMID 36292072, 2022). "Herein, we report biomarkers associated with RT in plasma of mice harboring an IDH1-mutated astrocytoma and which experienced a significant increase in survival as a result of RT." (PMID 36353533, 2022). "In a previous study by our group, a correlation of LOX expression level with IDH1 mutation status was found in diffusely infiltrative astrocytomas (grades 2 to 4)." (PMID 36076905, 2022). "Cyclin-dependent kinase inhibitor 2A/B (CDKN2A/B) homozygous deletion in IDH1/2 mutant astrocytoma associates with a poor prognosis, similar to WHO IV tumors." (PMID 34540693, 2021). "Our data support the notion that increased genome-wide DNA methylation levels are associated with improved outcome in this tumour type and indicate that the type of IDH1/2 mutation should be taken into account for prognostication of astrocytoma patients." (PMID 33740099, 2021). "In this respect diagnostic assays should be able to discriminate between the type of IDH-mutation present; non-R132H IDH1/2-mutations comprise ~ 10% of all IDH-mutations in astrocytomas." (PMID 33740099, 2021). "The first report validated the safety and therapeutic efficacy of NOA-16 in the patients newly diagnosed with malignant astrocytoma harboring the IDH1 mutation (NCT02454634)." (PMID 34356864, 2021). "The median EOR was larger in Oligodendroglioma than in Diffuse Astrocytoma IDH1/2 wild-type (92% vs. 83%; p = 0.002) and tended to also be larger in Diffuse Astrocytoma IDH1/2 mutated than in Diffuse Astrocytoma IDH1/2 wild-type (87% vs. 83%; p = 0.05)." (PMID 33976246, 2021).
astrocytomas (continued). "We found that astrocytoma patients with an IDH1 mutation have a unique molecular profile compared to IDH1-wildtype." (PMID 34503108, 2021). "Mutations in CHECK2, EGFR, PTEN, RYR2, and NF1 are instead associated with an IDH1-wildtype astrocytoma." (PMID 34503108, 2021). "In contrast, in ALT positive astrocytomas pTERT and IDH1 mutations appeared mutually exclusive and pTERT mutations were generally associated with IDH1 wild-type astrocytoma." (PMID 33547950, 2021). "Otherwise, considering the 10 years estimated OS, the percentage was similar amongst Diffuse Astrocytoma IDH1/2 mutated and Oligodendroglioma, and greater for Diffuse Astrocytoma IDH1/2 wild-type." (PMID 33976246, 2021). "A recent, multicenter study suggested that non-IDH1-R132H IDH1/2 mutations are associated with an improved survival for astrocytomas compared to their R132H-mutant counterpart, which provides a basis for analyzing these rare mutations." (PMID 34829476, 2021). "The most common mutation identified in astrocytomas was IDH1-R132H (29/30 IDH1-R132H, 1/30 IDH1-R132S)." (PMID 34020723, 2021). "The PDCs from the astrocytoma second recurrence maintained heterozygous IDH1 mutation through extensive passaging, as did the oligodendroglioma recurrence 3 PDCs." (PMID 32904945, 2020). "The PSS’s accuracy in predicting astrocytoma patients’ two-year survival was found to be 86.8%, while the accuracy of prediction using IDH1 mutational status was 81.1%." (PMID 33227903, 2020). "Within a histologic grade, IV astrocytoma cohorts, akin to lower-grade astrocytomas, a mutation in IDH1 or IDH2 carries the most significant prognostic value." (PMID 32640746, 2020). "Mutations found in IDH1/2 genes totaled 63.4% (N = 40) wherein IDH1 mutations were significantly associated with oligidendrioglioma (p = 0.005) and astrocytoma (p = 0.0002)." (PMID 33552543, 2020). "This is consistent with germline variants at 8q24.21, which are associated with IDH1- IDH2 mutated astrocytoma and oligodendroglial tumors." (PMID 31968687, 2020). "A highly significant association was observed between IDH1 status with respect to OG (p = 0.0002) and astrocytoma (p = 0.005)." (PMID 33552543, 2020). "The MMP-2 and GFAP proteins did not demonstrate any statistically significant expression differences between different malignancy grades and different IDH1 mutational status astrocytoma groups, or between the astrocytoma and healthy control groups." (PMID 33227903, 2020). "Comparison of ADC histogram profiles of IDH-1 mutated and IDH-1 wildtype astrocytomas revealed significant differences for Entropy, with higher values in case of muted IDH-1." (PMID 32158691, 2020). "Here, we successfully derived and characterized PDCs and scPDCs that maintain diagnostic molecular features and key oncogenic drivers of IDH1-mutant astrocytoma and oligodendroglioma." (PMID 32904945, 2020). "IDH1 mutations were most frequently present in tumors with OG (85.7%) and astrocytoma (71.4%), as compared with GBM (27.8%)." (PMID 33552543, 2020). "Our data suggests a dichotomy of mechanisms in astrocytoma depending on the presence of IDH1 mutations." (PMID 31960234, 2020). "Mutations in IDH1 or its homolog 2 (IDH2) have been identified as early molecular events in the development of astrocytomas and oligodendrogliomas, and they occur in various types of malignancies, including IDH-mutant glioblastoma (grade IV)." (PMID 31968687, 2020).
astrocytomas (continued). "Significant association was observed between IDH1 mutations and oligidendrioglioma (p = 0.005) and astrocytoma (p = 0.0002)." (PMID 33552543, 2020). "In adults, mutations in IDH1 or IDH2 confer a significant survival benefit in histologically lower-grade astrocytomas compared to their IDH-wildtype counterparts, and as such, is the most important prognostic factor in this group." (PMID 32640746, 2020). "Visual inspection showed absence of [11C] choline uptake in patients three and six, both with an IDH1-mutated astrocytoma (WHO grade II)." (PMID 31254208, 2019). "IDH1/2 mutations were found in both astrocytomas and oligodendrogliomas and portended a better outcome that IDH1/2-wild-type (wt) tumors." (PMID 31788444, 2019). "Approximately 40% of individuals with IDH1/2 mutated oligodendrogliomas and astrocytomas carry the germline rs55705857 G allele, compared with approximately 8% of the general population." (PMID 30823903, 2019). "Based on the genetic background of astrocytoma, mutations in gene IDH1, and specific copy number alterations in the genome, are two of the major molecular characteristics of astrocytoma." (PMID 30322114, 2018). "Low HAS2 immunostaining was associated with IDH1 mutation, a known positive prognostic factor in diffusely infiltrating astrocytomas." (PMID 29914429, 2018). "IDH mutations, most of the R132 codon of IDH1, are found frequently in a majority of astrocytomas and oligodendrogliomas cases." (PMID 30462709, 2018). "The majority (90%) of both astrocytomas and oligodendrogliomas carry a specific point mutation (R132H) in the IDH1 gene, which can be detected immunohistochemically with a mutation-specific antibody." (PMID 29098416, 2018). "ATRX alterations occur in the vast majority of lower-grade astrocytomas and IDH1-mutated (secondary) GBMs." (PMID 28654422, 2017). "In conclusion, we performed, for the first time, an integrated characterization of chromosomal CNA, microsatellite instability, and TERT/IDH1 mutational analysis in astrocytomas arising in the Brazilian population." (PMID 27172220, 2016). "In WHO grade II astrocytomas, reduction of postoperative tumor burden was prognostic for OS within the subgroup of IDH1-mutated, ≥40 % EOR tumors." (PMID 27344556, 2016). "IDH mutated glioma patients are significantly younger than those with IDH wild type, and IDH1/2 mutation is strongly associated with low grade astrocytomas." (PMID 26614510, 2016). "A total of 69% of GBMs presented TERT mutation, whereas IDH1 mutation was most frequent in diffuse (85.7%) and anaplastic (100%) astrocytomas." (PMID 27172220, 2016). "In studies pooling low-grade astrocytomas and oligodendrogliomas, the IDH1 mutation status was prognostic for overall and PFS." (PMID 26858939, 2016). "We therefore evaluated the prognostic impact of extensive, mainly intraoperative (i)MRI-guided surgery in low-grade astrocytomas stratified for IDH1 mutation status." (PMID 27344556, 2016). "This study sought to evaluate the prognostic impact of extensive surgery in a histologically well-defined cohort of WHO grade II astrocytomas stratified for IDH1 mutation status." (PMID 27344556, 2016).
astrocytomas (continued). "In the present study, we performed a molecular characterization in order to describe the genomic alterations and mutation status of the key TERT and IDH1 genes in astrocytomas arising in the Brazilian population." (PMID 27172220, 2016). "We previously demonstrated that the IDH1 c.G395A; p.R132H mutation is more frequently observed in higher-grade astrocytoma cases." (PMID 27834917, 2016). "Studies have shown that IDH1 mutation status is inversely related to tumor grade, with higher mutation rates in low grade astrocytomas compared to GBMs." (PMID 25714433, 2015). "The presence of IDH1 mutation in the majority of low grade astrocytomas confirms the neoplastic nature of the lesion and helps to differentiate the lesser cellular infiltrative tumor and /or tumor margin from gliosis particularly in a stereotactic biopsy." (PMID 27275230, 2015). "Our results demonstrated that IDH1 mutations occur at a high frequency in WHO grade II astrocytomas and oligodendrogliomas." (PMID 26115094, 2015). "Conversely, IDH1/2 mutations in Grade II-III astrocytomas are frequent while TERT promoter mutations are uncommon." (PMID 24722048, 2014). "We provide evidence that over 86% of oligoastrocytomas in this cohort contain genetic signatures representative of either astrocytoma (IDH1/2 mutations alone) or oligodendroglioma (TERT promoter/IDH1/2), signatures that we show are associated with OS." (PMID 24722048, 2014). "Novel alterations, including recurrent mutations in PIK3R1 and Notch family genes (NOTCH1, NOTCH2, NOTCH4, NOTCH2NL) are also revealed in the IDH1-mutated astrocytomas." (PMID 24140581, 2014). "In contrast, IDH1/2 mutations were observed in 78.4% of Grade II-III astrocytomas, but were uncommon in primary GBM." (PMID 24722048, 2014). "Recent studies revealed the important role of mutated IDH1 in the assessment of astrocytoma patient prognosis." (PMID 24511544, 2014). "In astrocytoma and oligodendroglioma, we detected higher 2-HG levels in rare IDH1 mutations than in the most common IDH1R132H alteration." (PMID 24529257, 2014). "In our study, polySia expression was shown to be associated with IDH1 mutation, one of the key features of astrocytomas." (PMID 25164322, 2014). "To identify the possible association between seizure occurrence and IDH1 mutation, we have retrospectively reviewed a total of 60 Chinese patients with LGGs, including 19 oligodendrogliomas, 19 oligoastrocytomas, and 22 astrocytomas." (PMID 24324372, 2013). "IDH1/2 mutations were also correlated with low-grade astrocytomas (15/24, 62.5%), and are infrequent in high-grade tumors (3/74, 4.1%) (p < 0.001)." (PMID 24079673, 2013). "More than 70 % of Stage II–III astrocytoma or oligodendroglioma tumors have mutations in either IDH1 or IDH2." (PMID 23229761, 2013). "This has led to the proposal of a common tumor progenitor cell for both oligodendrogliomas and astrocytomas, both harboring IDH1- mutations." (PMID 22844452, 2012). "Recently, we and others reported on a high rate of somatic IDH1- mutations affecting codon R132 in a large series of brain tumors including oligodendrogliomas, oligoastrocytomas and astrocytomas." (PMID 22844452, 2012). "IDH1 sequencing and loss of heterozygosity analysis was performed for 15 surgery samples of astrocytoma and early and late passages of cells derived from those and for 11 archival samples." (PMID 21326241, 2011).